IL24 (interleukin 24)
Diseases named in the same sentence as IL24 in open-access papers (continued):
Sharing a sentence is not in itself a finding about the gene and the disease.
breast cancer (continued). "There was a substantial increase in IL-24, an IL-4-induced cytokine with demonstrated targeted anti-breast cancer activity." (PMID 38203396, 2023). "In murine mammary cancer cells, TTs prevent angiogenesis by increasing interleukin-24 (IL-24) mRNA expression and decreasing IL-8 and vascular endothelial growth factor mRNA levels." (PMID 37240924, 2023). "IL-24 is a tumor-suppressor cytokine that selectively induces cell cycle arrest and apoptosis in a wide variety of human cancer cells, including breast cancer." (PMID 34944995, 2021). "IL-24 inhibits tumor cell growth by inducing apoptosis and/or cell cycle arrest in several types of cancer, including leukemia, breast cancer, and pancreatic cancer 24-26." (PMID 33456560, 2021). "Publicly available data showing that high expression of IL-24 at the protein level is related to longer overall survival in breast cancer patients also further supported our results (p = 0.00051)." (PMID 34944995, 2021). "Our study shows that IL-24 is a biomarker candidate for selecting patients and predicting the effects of E2 treatment in AI-resistant ER+ postmenopausal breast cancer." (PMID 34944995, 2021). "Amplification of IL19, IL20, and IL24 co-occurs in ~9% of breast cancer patients, while the rate of IL26 amplification is only 2.4%." (PMID 33456560, 2021). "As expected, the concentrations of IL-24 protein from all breast cancer cells treated with VG9-IL-24 was remarkably increased compared with that from normal cells (all P<0.01)." (PMID 31956348, 2020). "Interleukin-24 (IL-24) is a novel tumor suppressor cytokine that selectively induces apoptosis in a wide variety of tumor types, including breast cancer." (PMID 31956348, 2020). "Collectively, we constructed a recombinant vaccinia virus VG9-IL-24, which was armed with a potent tumor-suppressing gene IL-24, and demonstrated it exerted significant antitumor effects on breast cancer both in vitro and in vivo." (PMID 31956348, 2020). "Our data showed that vaccinia virus-mediated IL-24 exerts strong killing effects on various breast cancer cell lines; of note, it also has the cytotoxic effect on TNBC cells, such as MDA-MB-231, MDA-MB-453 and MDA-MB-468 cells." (PMID 31956348, 2020). "Significantly lower IL-24 expression predicted poorer prognosis in lung adenocarcinoma, breast cancer, head and neck squamous cell carcinoma, and lymphoma." (PMID 31921658, 2019). "In terms of breast cancer, it has been reported that oncolytic adenovirus carrying IL-24 exhibits obvious anti-tumor effect in an animal model of breast cancer." (PMID 31278126, 2019). "We treated MCF-7 human breast cancer cells with increasing concentrations of adenovirus vector expressing IL-24 (Ad.IL-24) for 72 h, and analyzed the expression of ATF4 protein by Western blot." (PMID 30424508, 2018). "IL-24 also inhibits angiogenesis in human lung tumor cells in vivo, and sensitizes breast cancer cells to chemotherapy." (PMID 30424508, 2018). "Overall, these results demonstrate for the first time that PKA is a key mediator of IL-24-induced apoptosis in breast cancer cells." (PMID 30424508, 2018). "Our studies show for the first time that cyclic adenosine monophosphate (cAMP)-dependent protein kinase A (PKA) activation is required for IL-24-induced cell death in a variety of breast cancer cell lines and this event increases ATF4 activity." (PMID 30424508, 2018).
breast cancer (continued). "BIRC5 and FOXM1 downregulation and IL24 induction was also evident in breast cancer patient datasets following taxane treatment." (PMID 28187446, 2017). "Nevertheless, the contrast between our findings and those in previous reports indicates that additional analysis into the role of IL-24 in obASCs through inhibition or knockdown studies would shed light on the effects of IL-24 on breast cancer cells." (PMID 29527228, 2017). "IL-24 has been shown to inhibit the growth of breast cancer cells through the activation of apoptotic pathways and the inhibition of angiogenesis." (PMID 29527228, 2017). "Following continuous exposure to breast cancer cells, the expression of IL-24 in obASCs also continued to increase with each serial coculture, whereas the levels of IL-24 were significantly reduced in lnASCs after the initial coculture." (PMID 29527228, 2017). "Enhanced tumor suppression was shown by nonreplicating bicistronic Ad vector expressing both ING4 and IL-24 genes employed for treatment of human non-small cell lung cancer, breast cancer, and hepatocarcinoma subcutaneous tumor xenografts." (PMID 27349517, 2016). "Using the MMTV-PyMT spontaneous mammary tumor model, we confirmed that exogenously introducing MDA-7/IL-24 using a Cancer Terminator Virus caused a reduction in tumor burden and also produced an antitumor “bystander” effect." (PMID 26474456, 2015). "In parallel, we previously reported that IL-24 can negatively regulate the PI3K/AKT signaling pathway in Ad-IL24-transduced lung and breast cancer cells." (PMID 26009991, 2015). "Further, we assessed the role of MDA-7/IL-24 in engaging the immune system to mount an anti-tumor immune response against mammary tumors." (PMID 26474456, 2015). "Our findings provide further direct in vivo evidence for the role of MDA-7/IL-24 in tumor suppression in breast cancer in immune-competent transgenic mice." (PMID 26474456, 2015). "Mechanistically, MDA-7/IL-24 exerted its tumor suppression effect on HER2+ breast cancer cells, at least in part, through PERP, a member of PMP-22 family with growth arrest and apoptosis-inducing capacity." (PMID 26460950, 2015). "Over-expression of mda-7/IL-24 in the HER2+ breast cancer cell line SKBR3 also induced perp mRNA levels." (PMID 26460950, 2015). "We report that mammary tumor development was significantly inhibited in MMTV-rtTA:IL24tet-on:MMTV-Her2/neu triple compound transgenic mice in which mda-7/IL-24 was over-expressed by means of a doxycycline inducible promoter." (PMID 26460950, 2015). "Recombinant human IL-24 (rhIL-24) reverses the chemoresistance in human breast cancer cell line MCF-7 cells and significantly suppresses the growth of ovarian cancer cell." (PMID 26528857, 2015). "At supra-physiological levels, MDA-7/IL-24 displays anti-cancer properties towards breast cancer including inhibition of tumor growth, invasion, metastasis, angiogenesis and tumor-initiating/stem cells." (PMID 26474456, 2015). "Since most MNU-induced tumors in rats contain activating mutations in Ha-ras, which arenot frequently detected in humans, we presently examined the effect of MDA-7/IL-24 on Her2/Neu-induced mammary tumors, in which the RAS pathway is induced." (PMID 26460950, 2015). "The ability of IL-24wt to modulate GSK-3 and β-catenin concurs with our previous report demonstrating that Ad-mediated IL-24 expression in breast cancer cells reduced the expression of these proteins." (PMID 26009991, 2015). "Our results provide a rationale for the prophylactic use of mda-7/IL-24 in the prevention as well as applications for therapy of HER2+ breast cancer." (PMID 26460950, 2015). "Overall, our results establish mda-7/IL-24 as a suppressor of mammary tumor development and provide a rationale for using this cytokine in the prevention/treatment of human breast cancer." (PMID 26460950, 2015).
breast cancer (continued). "Further studies revealed that IL-24 effectively inhibited proliferation and angiogenesis of cancer cells, even reduce the percentage of breast cancer-initiating/stem cells and mesenchymal stem cells (MSCs) in vivo." (PMID 26528857, 2015). "Recent studies in breast cancer-initiating/stem cells showed that MDA-7/IL-24 induced apoptosis and endoplasmic reticulum stress and inhibited self-renewal potential of breast cancer-initiating/stem cells by suppressing the Wnt signaling pathway." (PMID 26474456, 2015). "We utilized three transgenic mouse models to better comprehend the in vivo role of MDA-7/IL-24 in breast cancer." (PMID 26474456, 2015). "Specifically, we demonstrated significant inhibition of tumor development following injection of an adenovirus carrying mda-7/IL-24 into the main mammary ducts of rats induced to develop breast cancer by treatment with methylnitrosourea (MNU)." (PMID 26460950, 2015). "Our first strategy was to introduce MDA-7/IL-24 by adenoviral injection into mammary tumors arising spontaneously in MMTV-PyMT transgenic mice." (PMID 26474456, 2015). "We also crossed the MMTV-MDA-7 line to MMTV-Erbb2 transgenic mice and found that MDA-7/IL-24 overexpression delayed the onset of mammary tumor development in this model of spontaneous mammary tumorigenesis as well." (PMID 26474456, 2015). "In conclusion, our study shows that MDA-7/IL-24 can delay tumor onset as well as tumor progression in transgenic mice and contributes to an immune response against mammary tumors." (PMID 26474456, 2015). "Cytokine mda-7/IL-24 has been extensively investigated for selective antitumor effect on prostate cancer, lung cancer, ovarian cancer, breast carcinoma, colorectal cancer, and glioma." (PMID 26554307, 2015). "ING4/IL-24 gene therapy and radiotherapy suppressed cell proliferation and induced apoptosis in breast cancer cells." (PMID 24377906, 2013). "Treatment of human breast cancer xenograft with Ad-IL24 and radiation produced complete tumor regression." (PMID 24377906, 2013). "Induction of GADD family of genes was also demonstrated in Ad-IL24-treated glioblastoma multiforme, prostate cancer, breast cancer and in pancreatic cancer cells that resulted in tumor cell apoptosis." (PMID 24377906, 2013). "In another study, Ad-IL24 when combined with cyclooxygenase (COX)-2 inhibitor produced enhanced radiosensitization of breast cancer cells." (PMID 24377906, 2013). "As expected, 48 hours after infection of CNHK600-IL24, the concentration of IL-24 protein in supernatants of infected breast cancer cells was significantly elevated (3 ng/ml), whereas the level of IL-24 MRC-5 cells remained low." (PMID 22640485, 2012). "The oncolytic adenovirus armed with IL-24, which exhibited enhanced anti-tumor activity and improved survival, is a promising candidate for virotherapy of breast cancer." (PMID 22640485, 2012). "The expression of IL-24 in breast cancer cells and normal fibroblast was quantified by ELISA and western blotting assays." (PMID 22640485, 2012). "Thus, the IL-24/IL-20R axis plays an essential role in mediating the efficacy of calcipotriol in suppressing mammary tumor growth." (PMID 39782693, 2025). "Thus, CD4+ Th2 cell activation can suppress breast cancer by inducing antitumor IL-24–expressing TAMs in the TME, which can be leveraged in cancer immunotherapy." (PMID 39782693, 2025). "In breast cancer, IL-24 exerts an inhibitory effect on breast tumor development." (PMID 39782693, 2025). "Transcriptomic studies have shown that PVT can increase the level of Il-24 mRNA and downregulate the level of Cxcl10 mRNA in MDA-MB-231 cells, whereas IL-24 can inhibit the growth of various tumor cells, including breast cancer cells, and induce the apoptosis of tumor cells." (PMID 40076586, 2025).
breast cancer (continued). "Combined IL-24 and WP1066 treatment elicited more pronounced growth suppression in both MDA-MB-231 and HCC-1954 cells than WP1066 treatment alone, suggesting that IL-24 may sensitize breast cancer cells to WP1066." (PMID 40175348, 2025). "Interestingly, IL-24 is the most significantly upregulated cytokine in calcipotriol-treated mammary tumors." (PMID 39782693, 2025). "Likewise, the efficacy of ZD55‐IL‐24, an oncolytic adenovirus for IL‐24 delivery, in combination with the chemotherapeutic drug paclitaxel was examined in breast cancer models." (PMID 40338095, 2025). "In addition, we identified a positive correlation between the expression of TXNIP and interleukin-24 (IL-24), a molecule that induces cancer-specific apoptosis in several breast cancer cell lines." (PMID 40175348, 2025). "Calcipotriol treatment leads to IL-24 expression by TAMs in mammary tumors." (PMID 39782693, 2025). "Furthermore, activated T helper (Th) cells stimulate macrophages to produce IL-24, leading to the suppression of mammary tumor growth." (PMID 40607413, 2025). "In addition to identifying the novel interaction between CAST and TXNIP, our study revealed that overexpressing TXNIP increases IL-24 levels while knocking down TXNIP decreases IL-24 expression in breast cancer cells." (PMID 40175348, 2025). "Moreover, transgenic animal models of breast cancer involving production and secretion of IL-24 by the mouse mammary gland have documented protective effects against breast cancer development." (PMID 39744942, 2025). "IL-24 is involved in breast cancer progression through the cAMP-dependent PKA pathway, which regulates the p38MAPK pathway, suggesting that the p38MAPK signaling pathway may be the downstream of PKA." (PMID 32273830, 2020). "Based on these studies, we sought to determine whether IL-24 activates the extrinsic pathway of apoptosis in MCF-7 breast cancer cells, and whether the IL-24 induction of extrinsic apoptotic pathway is PKA-dependent." (PMID 30424508, 2018). "And PKI inhibited IL-24-mediated killing in all breast cancer cell lines." (PMID 30424508, 2018). "Exogenous expression of IL24 by liposomes or adenoviruses specifically inhibited cancer cell growth and induced tumor-specific apoptosis in a broad spectrum of solid tumors, including breast cancer, neuroblastoma, and HCC." (PMID 28109288, 2017). "Finally, to determine the relevance of the presence of MDA-7/IL-24 on tumor onset and progression of a model of spontaneous mammary tumor development, we generated MMTV-MDA-7/MMTV-Erbb2 compound transgenic mice." (PMID 26474456, 2015). "We generated tet-inducible mda-7/IL-24 transgenic mice to investigate whether mda-7/IL-24 expression could suppress development of Her2/Neu mammary tumors in compound immunocompetent transgenic mice." (PMID 26460950, 2015). "Since Ha-ras mutations are not frequently detected in humans, in the present study we investigated whether mda-7/IL-24 could inhibit development of Her2/Neu-induced breast cancer." (PMID 26460950, 2015). "Presence of MDA-7/IL-24 in the injected tumors validated that Ad5-CTV could replicate within the mammary tumors." (PMID 26474456, 2015). "In vitro studies showed that MDA-7/IL-24 induced G2/M cell cycle arrest in breast cancer cells via downregulation of AKT-GSK3β and upregulation of cyclin-dependent kinase inhibitor and apoptosis by activation of caspase-dependent signaling pathways and BAX signaling." (PMID 26474456, 2015). "Furthermore, significantly lower expression of IL-24 was also noted in tumors from patients who died of breast cancer compared to those who remained disease free." (PMID 22640485, 2012). "Similarly, the expression of IL-24 protein in the lysates of breast cancer cells was significantly increased, whereas the IL-24 levels in normal fibroblasts remained difficult to detect." (PMID 22640485, 2012).
breast cancer (continued). "However, considering the unique characteristics of IL-24 to induce apoptosis, inhibit angiogenesis, increase T cell fitness, and suppress metastatic potential in breast cancer and other tumor types, there are likely ample avenues for potential synergistic therapies." (PMID 38203396, 2023). "IL-24 and IL-22R were reduced and correlated inversely to the elevated levels of lymphangiogenic markers, suggesting that the lack of IL-24 could enhance lymphangiogenesis, tumor growth, and dissemination in breast cancer." (PMID 35885529, 2022). "We also found that the expression level of IL20RA ligands IL-19, IL-20, and IL-24 was dramatically elevated in the serum of breast cancer patients compared to that of healthy donors, indicating that IL20RA signaling may play an important role in the progression of cancer." (PMID 33456560, 2021). "Next, we explored whether PKA is involved in IL-24-induced apoptosis in breast cancer cells." (PMID 30424508, 2018). "This enhanced immune activation was present in MDA-7/IL-24 treated tumors as well as non-treated tumors, indicating that a systemic antitumor immunity augmented by MDA-7/IL-24 may also contribute to its therapeutic activity in this breast cancer transgenic mouse model." (PMID 26474456, 2015). "First, we determined if IL-24 activates PKA in human prostate cancer cell lines, as shown in human breast cancer cells." (PMID 40072085, 2025). "Thus, IL-24 upregulation may play a protective role in human breast cancer." (PMID 39782693, 2025). "We uncover the efficacy of topical calcipotriol for breast cancer therapy, which relies on inflammatory CD4+ Th2 cell-macrophage crosstalk to induce IL-24-mediated tumor cell death." (PMID 39782693, 2025). "First, when COTL-1 was re-expressed in mesenchymal mouse breast cancer cells (FE 1.2) and human MCF7 breast cancer cells, it led to the activation of the growth-suppressor gene interleukin-24 (IL-24)." (PMID 37894372, 2023). "For the first time, we show that IL-24 increases intracellular cAMP levels, and activates PKA to exert its killing effect through the extrinsic apoptotic pathway in MCF-7 breast cancer cells." (PMID 30424508, 2018). "We found that with increasing concentrations of IL-24, phosphorylation levels of PKA substrates substantially increased 72 h post-infection in MCF-7 breast cancer cells." (PMID 30424508, 2018). "We previously demonstrated that recombinant adenovirus-mediated mda-7/IL-24 expression in the mammary glands of carcinogen-treated (methylnitrosourea, MNU) rats suppressed mammary tumor development." (PMID 26460950, 2015). "They provided mechanistic insight into the signaling mechanism of MDA-7/IL-24 and show that the tumor suppressive effects observed in HER2+ breast cancer cells were mediated through PERP, a member of the GAS-3/PMP-22 family of tumor suppressors." (PMID 26474456, 2015). "The role and mechanism of action of MDA-7/IL-24 in tissue culture and athymic xenograft models of breast cancer have previously been studied; however few studies evaluated the role of MDA-7/IL-24 in an immune competent transgenic model." (PMID 26474456, 2015). "Follow-up studies from our collaborators laboratory showed IL-24 inhibited the PI3K and Wnt/beta-catenin signaling pathway in breast cancer cells." (PMID 24377906, 2013). "Likewise, other studies have documented that the administration of IL‐24 results in decreased invasive and migratory capacity in Ishikawa cells as well as MDA‐MB‐231 breast cancer cells." (PMID 40338095, 2025). "In addition, IL-24 can exert antitumor effects through CXCR4/CXCL12, and CXCL10, CXCL12 and CXCR4 are highly expressed in breast cancer tissues." (PMID 40076586, 2025).